CCR4 (C-C motif chemokine receptor 4)
Diseases named in the same sentence as CCR4 in open-access papers (continued):
Sharing a sentence is not in itself a finding about the gene and the disease.
tumor (continued). "Collectively, these findings provide compelling evidence, which suggests that higher accumulation of Treg cells in local tumor maybe a consequence of elevated levels of CCL22 in the tumor microenvironment attracting CCR4-expressing Treg cells." (PMID 26020249, 2015). "CCR4(+) Tregs protect CCR4(+) tumor cells from being attacked by antitumor host immune cells." (PMID 25110692, 2014). "It was also shown that the circulating T-regulatory cells display significantly higher expression of CCR4 than the tumor infiltrating T-regulatory cells suggesting that they could be recruited via the CCR4/CCL22 axis." (PMID 24384839, 2013). "Using mouse models, several approaches, including the use of specific antibodies, antagonists, or siRNA, have been used to block the CCL22/CCL17 – CCR4 axis, resulting in reduction in Treg frequencies and a concomitant increase in anti-tumor activity (40, –42)." (PMID 23874342, 2013). "Furthermore, this study showed that the AAV8-h1567 minibody inhibited the primary CCR4+ tumor burden, suppressed local metastasis and prolonged the survival time in tumor-bearing SCID-BEIGE mice." (PMID 22973452, 2012). "This Treg recruitment may involve a CCR4-dependent trafficking induced by CCL22 released by tumor cells and immune cells infiltrating the tumors such as macrophages and DCs." (PMID 22110524, 2011). "Thus, we hypothesized that CCR4‐expressing CD39+ Tregs in peripheral blood could be chemotactically attracted to the tumour microenvironment to exert immunosuppressive effects, leading to immunotherapy resistance and a worse prognosis in our study." (PMID 40000397, 2025). "Moreover, whether M2-like macrophages-derived CCL17 could exert its tumor-promoting effects via CCR4-mediated ERK/PD‐L1 signaling was thoroughly elucidated." (PMID 39473097, 2025). "In an in situ PDAC mouse models, spMEXO could exert potential therapeutic effects by promoting the maturation of DCs, activation of CTLs, secretion of anti-tumor cytokines and blocking recruitment of Tregs by DCs through the CCR4/CCL22 axis, successfully inhibiting tumor growth." (PMID 38298192, 2024). "Anti-CCR4 mAb may be an ideal treatment approach for patients with CCR4 positive tumours." (PMID 38475858, 2024). "Furthermore, we could show that directing T cells into the tumor-draining lymph node via CCR4 can enhance therapeutic efficacy." (PMID 37301772, 2023). "One possible explanation of how tumor cells become resistant to transcription blockade by epirubicin is that they contain stored mRNA in condensates acting as a reservoir to maintain gene expression; simultaneously, mRNA decay initiated by the major deadenylase CCR4 function is altered in them." (PMID 37958852, 2023). "Furthermore, CCR4 was significantly correlated with tumor infiltration of B cells, CD8+ T cells, CD4+ T cells, and macrophages, while TMCO1 was significantly correlated with CD8+ T cells, and SPACA4 was significantly correlated with B cells, CD8+ T cells and Neutrophils." (PMID 36671475, 2022). "Hence, apart from targeting tumor cells, CCR4 CAR-T cells may also eliminate Tregs to facilitate the migration of immune cells into the tumor microenvironment, thereby augmenting anti-lymphoma activity of the therapy." (PMID 36059451, 2022). "Besides, targeting CCR4 to block this newly identified signaling may help in the development of alternative new strategies for suppression of HNSCC tumor metastasis." (PMID 35177591, 2022). "Indeed, CCR4 antagonism in combination with sorafenib showed enhanced anti-tumor efficacy by transforming the immune landscape toward anti-tumor immunity through overall reduction in Tregs, diminishing proportions of CCR4+ TIL-Tregs, decreasing PD-1+CD8+ T cells, and enhancing IFN-γ+CD8+ T cells." (PMID 36613878, 2022).
tumor (continued). "While clinical efficacy did not correlate with PDL-1 or CCR4 expression levels on tumour cells, the number of TIL or the mutational burden, Mogamulizumab reduced the proportion of Treg and increased the proportion of CTL in on-treatment biopsies compared to baseline." (PMID 34439389, 2021). "Moreover, their selective accumulation within the tumor site may suggest that selective depletion of CCR4+ or CCR8+ Tregs may enhance anti-cancer immunity while having a very limited effect on Tregs in the periphery." (PMID 34944943, 2021). "We have also shown that co-injection of compound 22, a CCR4 antagonist, with cancer vaccines inhibits Treg cell recruitment into vaccination sites and Treg-mediated DC suppression, resulting in enhanced induction of tumor-specific CTLs in a murine melanoma model." (PMID 34885241, 2021). "Thus, it seems that LDN, besides expressing PD-L1, could also indirectly exert immunosuppression towards T lymphocytes, possibly via CCR4+ Tregs, which in turn contribute to inhibit the activity of CTLs, and consequently anti-tumor responses." (PMID 34853660, 2021). "Therefore, CCR2b and CCR4 were functional in response to Mcp-1 secreted by tumor cells in vitro." (PMID 33777013, 2021). "Thus, the CCR4 axis may be involved in Treg cell expansion in the draining lymph nodes and Treg-mediated DC suppression in the tumor microenvironment." (PMID 34885241, 2021). "Thus, in certain types of cancer, CCR4 may play a role in anti-tumor immunity not only by recruiting Th17 cells into tumor tissues but also by promoting Th17 cell expansion in the draining lymph nodes with subsequent Th17-mediated CTL induction." (PMID 34885241, 2021). "Thus, CCR4 may also substantially contribute to anti-tumor immunity through the expansion of Th17 cells and subsequent induction of tumor-specific CTLs in certain types of cancer." (PMID 34885241, 2021). "Notably, TAMs also produce CCL17 and CCL22 to promote migration of CCR4+ Tregs to the tumor site." (PMID 32707850, 2020). "In addition to expression in most CD4+CD25+ ATLL, CCR4 is expressed in approximately 30–65% of PTCL tumor cells, including high expression (~ 65%) in ALK-negative ALCL, variable expression (30–40%) in PTCL/NOS, AITL, and transformed MF, while rarely expressed in ENKTL or ALK-positive ALCL." (PMID 32448357, 2020). "Tumor associated macrophages (TAMs) and myeloid suppressor cells (MDSCs) release chemokines, such as CCL17, CCL22, CCL5, CCL6 or CCL28, depending on the tumor type, to attract Tregs expressing the chemokine receptors CCR4, CCR5, CCR10 and CXCR3 from secondary lymphoid tissues to the tumor." (PMID 32937953, 2020). "Moreover, TNF alpha promotes tumor-induced immunosuppression via induction of aberrant CCR4 expression and may represent a new target for immune treatment of GC in the future." (PMID 33182840, 2020). "CCR4 is expressed on Tregs to drive their migration to and mitigate inflammatory responses in tissue, and while a reduction in Tregs may boost immunity in the tumor microenvironment, it may simultaneously create autoimmunity in tissue sanctuaries." (PMID 31616431, 2019). "Additionally, tumor cells or tumor‐associated macrophages (TAMs) could also secrete CCL17 and CCL22 which are able to recruit CCR4+ regulatory T cells (Treg)." (PMID 31231980, 2019). "If tumor development associated with Not3 disruption is linked to the CCR4-NOT complex functionality, downregulation of selected genes could also rescue tumor development in the sensitized + twin-tumors." (PMID 30144809, 2018). "Moreover, CCL17 and CCL22 can also attract CCR4-expressing Treg cells, which may further suppress cytotoxic T-cells and prevent tumor immunosurveillance of the ATL cells." (PMID 29915722, 2018). "However, in vivo study, the significant inhibition of tumor could be observed by CCR4 knockdown in xenograft tumors model." (PMID 28959024, 2017).
tumor (continued). "Similarly, CCR4 overexpression in HepG2 cells (HepG2/CCR4) may lead to acceleration of tumor growth in xenograft model compared with HepG2/Vector cells." (PMID 28959024, 2017). "There may be a very fine balance between the impairment of Ccr4-Not function that can ensure survival of tumor cells with genomic lesions, or instead more severe ccr4-not mutations that will be toxic." (PMID 28588606, 2017). "Therefore, we postulated that HNSCC-circulating aTreg cells could be recruited to the tumor microenvironment by endogenous MCP-1 through binding to CCR4." (PMID 27177223, 2016). "Indeed, the anti-CCR4 mAb mogamulizumab, which showed significant anti-tumor activity against ATL cells in the NOG mice via enhanced antibody-dependent cell-mediated cytotoxicity (ADCC), has been developed and subsequently approved for the treatment of relapsed or refractory ATL in Japan." (PMID 26597716, 2015). "CC chemokine receptor 4 (CCR4) represents a potentially important target for cancer immunotherapy due to its expression on tumor infiltrating immune cells including regulatory T cells (Tregs) and on tumor cells in several cancer types and its role in metastasis." (PMID 25080123, 2014). "Indeed, a subset of malignant T cells in some CTCL have been shown to act as CCR4+ Tregs to suppress anti-tumor responses and may fuel disease progression." (PMID 22973452, 2012). "Tumor cells, along with other stromal and immune cells in the TME, secrete chemokines including CCL22, CCL20, and CXCL12, which bind to CCR4, CCR6, and CXCR4 on Tregs and direct their recruitment and activation within the TME." (PMID 41890756, 2026). "NicheNet indicated that tumor‐derived chemokines (CCL5, TGFB1) interacted with Tregs receptors (CCR4, CCR5, CXCR3), promoting the Treg recruitment." (PMID 41028931, 2025). "Notably, approximately 74% of Tregs isolated from the peripheral blood of GBM patients express CCR4, compared with only about 43% in healthy individuals, suggesting that GBM may induce or upregulate CCR4 expression on Tregs through soluble factors in the tumor milieu." (PMID 40867165, 2025). "In BC, HAT1 from the GNAT family induces histone H3 acetylation at the CCR4 promoter in Tregs through the FOXP3/HAT1 complex, promoting Tregs infiltration in the tumor microenvironment and tumor cell immune evasion." (PMID 40313963, 2025). "By binding to CCR4-expressing tumor cells, it induces ADCC and eliminates tumor cells, while also depleting immunosuppressive Tregs, thereby potentially enhancing anti-tumor immunity." (PMID 40940718, 2025). "Previous studies have shown that CCR4, binding with CCL17/CCL22, can induce Treg cell enrichment within the tumour microenvironment (TME)." (PMID 40000397, 2025). "Importantly, though, with our PCLS and in situ data, we cannot distinguish whether the ZEB1-dependent CTL abundance (in situ) and the CCR2/CCR4-dependent tumor control (PCLS) are regulated by a direct recruitment of CD8 + T cells by CCL2 and/or CCL22 or other alternative mechanisms." (PMID 40595293, 2025). "Tumor cells and stromal cells recruit Tregs to the tumor site primarily by secreting chemokines such as CCL22, CCL17 (binding to CCR4 on Tregs), and CCL28 (binding to CCR10)." (PMID 40698080, 2025). "Chemokine gradients—particularly involving receptors such as CCR4, CCR8, CCR10, and CXCR3—mediate Treg migration from the thymus to sites of inflammation or tumor." (PMID 40867165, 2025). "CD36 displayed strong positive correlations with immune receptors such as CCR1, CCR2, CCR4, CXCR1, and CXCR2, indicating its potential role in amplifying chemokine-receptor interactions and shaping immune cell trafficking within the tumor microenvironment." (PMID 41550652, 2025). "CCR4 induces chemotaxis in response to its target chemokines, CCL17 and CCL22, which are often upregulated in tumor microenvironments." (PMID 38254876, 2024).
tumor (continued). "The multivariate Cox proportional regression model identified significant predictors as independent prognostic factors for OS: CCL17-T high, CD34 high, CCR4 + CD73 + ≥ 13, CCR4-T high, CD73-T high, HHLA2, MVI, Treg/CD8 ≥ 1, and tumor size ≥ 5 cm." (PMID 38914802, 2024). "Specifically, SOX12 transactivated CCL22, which resulted in the accumulation and enhanced activity of CCR4+Tregs within the tumor, whereas SOX18 up‐regulated CXCL12 expression, attracting CXCR4+TAMs and CXCR4+Tregs into the tumor." (PMID 39072947, 2024). "In this study, we established a correlation between high expression levels of CCR4, CCL17, CD73, and HHLA2 in tumor tissues and the poor prognosis in HCC patients." (PMID 38914802, 2024). "CyTOF analysis showed that compared with the Ki67− counterparts, Ki67+ Tregs expressed higher levels of CCR4 and CCR5, receptors for the chemotactic factors CCL22 and CCL5 that are mainly produced by tumor cells, macrophages and DCs in the TME." (PMID 39438442, 2024). "For instance, CCR4 binds with ligands like CCL17 and CCL22 secreted by tumor cells, facilitating Treg infiltration." (PMID 38500876, 2024). "Another approach to recruiting T cells into tumor is to use constructs expressing a chemokine receptor, such as CCR2, CCR2b, CXCR3, CCR4, CCR7, CXCR2, or CXCR4, which can interact with the relevant tumor-derived chemokine." (PMID 38927974, 2024). "Treg cells highly express certain chemokine receptors (CCR4, CCR5, CCR8, CCR10), which facilitates their preferential migration to the tumor microenvironment." (PMID 38500876, 2024). "Recent studies have found that the CCR4 antagonist can enhance anti-tumour immune activity by reducing Tregs aggregation in the TME, and the combination of CCR4 inhibitor and CTLA-4 has a more significant effect." (PMID 38475858, 2024). "The CCR4/CCR6 chemokine system score was lower in tumor regression grading (TRG) of grade 0/1 compared to patients with TRG2/3, suggesting that the CCR4/CCR6 chemokine system would be a potential biomarker." (PMID 39703499, 2024). "These CCR4-depleted anti-CCR4 CAR T-cells enriched in Th1 and CD8+ T-cells led to potent anti-tumor activity against CCR4-expressing T-cell malignancies in mice." (PMID 39456582, 2024). "On the other hand, CD8+T cells can induce in situ proliferation of Tregs, which can also recruit Tregs into the tumor by secreting CCL22 and binding with CCR4 on the surface of Tregs." (PMID 38390329, 2024). "CCR4 and CCR8 have recently been identified as being more selectively expressed on tumor-reactive eTregs." (PMID 39227959, 2024). "This study seeks to investigate the clinical significance of CCR4, CCL17, CD73, and HHLA2 in HCC, exploring their interconnectedness within the tumor immune microenvironment." (PMID 38914802, 2024). "Several chemokine ligands are expressed by the tumor: CCL17 and CCL22 promote recruitment of CCR4+ Tregs, while CXCR3—along with its ligands, CXCL9 and CXCL10—drives cytotoxic lymphocyte trafficking into the GBM tumor site." (PMID 37443804, 2023). "In this study, we overexpressed two chemokine receptors, CCR4 and CCR2B, that are naturally found on T regulatory cells and tumor-resident monocytes, respectively, on NK cells." (PMID 36834542, 2023). "Tumour-infiltrating macrophages and tumour cells can produce chemokine ligand 22 (CCL22), which attracts cells expressing CCR4 to the tumour tissue." (PMID 38259489, 2023). "Role of CCR4 is being extensively studied in different types of cancers including HCC where it induces cell migration and promotes tumor growth and metastasis." (PMID 37081509, 2023). "In contrast to Th1 cells, Th2 cells express CCR3, CCR4, and CCR8 receptors on their surface and can promote tumor progression by exerting immunomodulatory functions in response to stimulation by the corresponding ligands." (PMID 37063892, 2023). "Mogamulizumab, an anti-CCR4 antibody, targets CCR4 and induces an ADCC reaction leading to tumor cell death and lysis." (PMID 36776886, 2023).
tumor (continued). "Mechanistically, TAM-secreted C-C motif chemokine ligand 17 (CCL17) and CCL22, via membrane receptor CCR4, activated the PI3K/AKT pathway in CRC tumor cells." (PMID 37658050, 2023). "Instead, organ infiltration and therapeutic efficacy were largely dependent on transduction with CCR4 in the lymph node-homing batch and CCR6 in the tumor-homing batch." (PMID 37301772, 2023). "Studies have shown that Tregs express a variety of chemokine receptors, such as CCR4, CCR5, CCR8 and CCR10, which can respond to a variety of chemokines released during tumor growth, and then participate in the migration of Tregs to tumor tissues." (PMID 37950246, 2023). "Tumor tropism of adoptively transplanted T lymphocytes by controlling tumor chemokine release to glioblastoma expressing CCL2, (a ligand for CCR4) has been demonstrated." (PMID 36721153, 2023). "The other batch contained CCR4 and CCR7, which conveyed T cell enrichment in the tumor-draining lymph nodes." (PMID 37301772, 2023). "As CCR4 is the shared receptor for both CCL17 and CCL22 and is reported to be overexpressed in tumor cells, we next examined its expression on the membrane of CRC cells and reproducibly detected strong signals in the isolated membrane fractions." (PMID 37658050, 2023). "Having said this, both HIV-specific co-receptors CCR4 and CCR5 have ties to tumor tendencies and share similar oncological pathways." (PMID 37489388, 2023). "A common predicted interaction involved CCL5 binding to CCR4 that is highly expressed on malignant T cells at all stages of CTCL, thus recruiting them at the tumor site." (PMID 37669110, 2023). "According to our results, TAMs‐released CCL22 stimulates the CCR4/FAK/AKT/Gli1 signaling in ESCC cells, providing a novel TAMs/intratumoral axis in tumor progression." (PMID 37846367, 2023). "Binding of CCL22 with CCR4 enhances T-cell dendritic cell binding and increases CTL activation, while enhancing tumor cell responses to IFN-γ." (PMID 36674931, 2023). "In malignancy, CCR4-expressing Treg interacts with CCL17 and CCL22-secreting tumor cells, with resultant impairment of host antitumor immunity." (PMID 35464471, 2022). "This review briefly characterizes CCR4 and its ligands (CCL17, CCL22, and CCL2), and their contributions to immunological and neoplastic diseases." (PMID 36555280, 2022). "CCR4, CCR8, CCR10, and CXCR3 induce Treg cell migration to the tumor microenvironment in response to CC and CXC chemokines: CCR4 is bound by CCL17 and CCL22, CCR8 is bound by CCL1, CCR10 is bound by CCL28,and CXCR3 is activated by CXCL9/10/11." (PMID 36012113, 2022). "As the depletion of Treg cells significantly reduces tumor burden, strategies targeting receptors (CCR4, CD25, CTLA-4, CCR8) preferentially expressed on tumor infiltrating Tregs are currently being evaluated in clinical trials." (PMID 36498469, 2022). "Administration of anti-CCR4 monoclonal antibody in vivo markedly decreased the Tregs fraction, augmented the responses of NY-ESO-1 specific CD8+ T cells, and evoked the anti-tumor immune responses." (PMID 35585567, 2022). "Results demonstrated that CXCR6 had more effective anti‐tumour responses with prolonged tumour rejection occurring in 33.3% of mice, whereas mice treated with CXCR3 or CCR4 had only 16.7%–0% prolonged tumour rejection." (PMID 36495108, 2022). "Tregs are recruited through the binding of CCR4 on Tregs surface and CCL22 released by GBM tumor cells and CD163+ TAMs, induced by tumor-derived CCL20 and osteoprotegerin." (PMID 35269652, 2022). "Tumour cells or infiltrating innate leukocytes release chemokines such as CCL17 and CCL22 to promote the migration of thymic Tregs expressing receptors such as CCR4, CCR5, and CCR8 from the secondary lymphoid tissues to the site of tumour." (PMID 35493450, 2022). "In TILs from the primary tumor site in five patients with OSCC, 4.19% of CD8+ T-cells and 11.4% of CD4+ T-cells expressed CCR4." (PMID 36522365, 2022).